ITGA7 (integrin subunit alpha 7)
Diseases named in the same sentence as ITGA7 in open-access papers (continued):
Sharing a sentence is not in itself a finding about the gene and the disease.
tumor (continued). "Interestingly, IHC result showed that the frequency of ITGA7+ cells was markedly enriched in cisplatin-treated tumours." (PMID 27924820, 2016). "The expression of these model genes (with the exception of ITGA7) is predominantly significantly positively correlated with macrophage infiltration, whereas it was significantly negatively correlated with the infiltration of anti-tumor immune cells, such as activated NK cells and CD8+ T cells." (PMID 41235257, 2025). "Interestingly, high-frequency ITGA7+ cells (>0.6%) was significantly associated with OSCC stemness such as cell differentiation, advanced clinical stage, tumour invasion and lymph node metastasis, suggesting that ITGA7 might play roles in regulating stemness." (PMID 27924820, 2016). "The result showed that ITGA7 could markedly enhance tumour cell mobility." (PMID 27924820, 2016). "Compared with control group, knockdown of ITGA7 could effectively suppress tumour initiation." (PMID 27924820, 2016). "In LMS, alterations in ITGA7 expression can disrupt these cell–ECM interactions, facilitating tumor cell detachment, invasion, and metastasis." (PMID 40076599, 2025). "There were several transcripts showing elevated expression in GBM stromal cell types versus stromal cell types in the grade III tumor, including IGFBP2 (ECM glycoprotein), ANXA1 (ECM-affiliated), ITGA7 (integrin), and SRGN (proteoglycan)." (PMID 41366031, 2025). "Here, we highlight tumor-derived sEV as a critical mediator for CAF-like activation of omental ADSCs and elucidate the central role of the miR-320a/ITGA7/TGF-beta axis in facilitating such activation and OC metastasis." (PMID 38233863, 2024). "In CRC, diverse circRNAs, such as circIFT80, circ_0053277, circ-ITGA7, circ_001917, have been reported to mediate CRC development via altering tumor cell growth, migration, EMT and angiogenesis." (PMID 34253241, 2021). "ITGA7 and NID2 promoter regions were bisulfite sequenced in one normal sample and four tumor samples and the results confirmed MSRE-PCR findings in all cases." (PMID 33500458, 2021). "Patients with ITGA7 high expression presented poorer pathological differentiation, larger tumor size, and more advanced TNM stage compared with patients with ITGA7 low expression." (PMID 31418948, 2019). "Previous studies support the assumption that alteration of the ITGA7 expression level and integrin redistribution processes, observed during long-term treatment, might be coupled to functional changes of the integrin molecule, driving resistant tumor cells to high motility." (PMID 29721158, 2018). "In the present study, we find that ITGA7+ cells to be sporadically expressed in clinical OSCC specimens and that the presence of ITGA7+ cells is closely correlated with aggressive tumour behaviour and poor outcome." (PMID 27924820, 2016). "The result found that ITGA7-overexpressed EC109 and KYSE30 cells displayed significantly stronger tumour initiation ability than their control cells." (PMID 27924820, 2016). "Expression of ITGA7 was analyzed by immunohistochemistry (IHC) on a tissue microarray (TMA) consisting of 300 paired OSCC and non-tumour clinical samples." (PMID 27924820, 2016). "From the Human Tumor Metastasis RT-PCR array with ATAD2 siRNA-treated cells, we identified APC, ITGB3, FXYD5, ITGA7 and CTNNA1 (α-catenin), which are related to cell adhesion; among these, the expression of APC and CTNNA1 changed by at least 3-fold." (PMID 24552534, 2014). "Among the inactive NBC-hom-related genes, we want to highlight the presence of proteins involved in interactions with the microenvironment, such as ADAM12, ITGA7, SH3PXD2A, and TNXB, since the tumor microenvironment is known to play a key role in MCL growth and therapy resistance." (PMID 41524027, 2026).
tumor (continued). "In addition, ITGA6 is relevant for binding laminin‐111 and ‐211, while ITGA7 is more relevant for laminin‐211, further supporting the role of laminin‐111 and ‐211 in SHH tumours." (PMID 33206391, 2021). "The only significant finding was nuclear ITGA7 demonstrated an extremely weak, and only just significant, negative correlation with tumour grade (Spearman’s coefficient −0.12, p = 0.04), although significance was lost after correction for multiple testing." (PMID 34253873, 2021). "Percentage of ITGA7+ cells (5.64±4.15%) was significantly enriched in tumours treated with chemotherapy, as compared with tumours without (0.64±0.74%)." (PMID 27924820, 2016). "Tumor stromal pathways are also in evidence with the common genes including; TLR4, TLR7, HLA-DRA, HLA-DQA1, CXCR4, FOS and TGFB2 (immune surveillance and chemokine pathways) and NF2, ITGA7, PGF, ITGA4, PDGFD and PARVA (focal adhesion)." (PMID 23226201, 2012). "To obtain further evidence in support of our hypothesis that ITGA7+ cells confer chemoresistance in OSCC tumours, we established a chemoresistant OSCC xenograft model by treating KYSE520 subcutaneously developed tumours in NOD/SCID mice with varying doses of cisplatin from 0 to 5 mg kg−1." (PMID 27924820, 2016). "Furthermore, we confirmed the downregulation of ITGA7, which was reported to be epigenetically deregulated in MPM and suggested as therapeutic and prognostic marker, and the downregulation of NF2, altered in almost half of MPM tumours with an important prognostic impact." (PMID 27835874, 2017). "The negative correlation between cytoplasmic ITGA7 protein level and RCC adhesion and migration properties of Caki-1 and KTCTL-26 indicate that ITGA7 is a tumor suppressor." (PMID 29721158, 2018). "By comparing differentially expressed genes affected by non-CG methylation between tumour and corresponding non-tumour tissues in oesophageal squamous cell carcinoma (OSCC), we find that Integrin α7 (ITGA7) is characterized as a potential cancer stem cell (CSC) marker." (PMID 27924820, 2016). "ITGA7-expressing cells were detected in most of these informative OSCC cases, with expression ranging from 0 to 5%; while ITGA7 expression could not be detected in any of the corresponding non-tumour tissues." (PMID 27924820, 2016).
cancer (27 papers, 2012 to 2025). A tumor composed of atypical neoplastic, often pleomorphic cells that invade other tissues. "The overexpression of ITGA7 correlates with worse overall survival in certain cancers, while downregulation is associated with a poor prognosis in others." (PMID 40076599, 2025). "We concluded that reduced ITGA7 was associated with cancer cell resistance to epirubicin, which is compatible with our clinical data demonstrating low ITGA7 expression was associated with poor outcomes after chemotherapy." (PMID 34253873, 2021). "We found relatively low ITGA7 expression specifically within cancer cells to be associated with poor patient outcomes after chemotherapy, which was concordant with reduced expression indicating increased stem-like properties including chemoresistance." (PMID 34253873, 2021). "ITGA7, which encodes the adhesion molecule integrin α7, was selected since integrins have been described as playing an important role in cancer progression as well as normal cell processes through ECM binding and transduction of cellular signaling." (PMID 32033262, 2020). "Given that integrin α7 is low in xenograft cells, but is high on mouse cancer-associated stromal cells, it is possible that ITGA7 plays a complex role mediating xenograft-microenvironment interactions." (PMID 30696911, 2019). "Notable downregulated genes included Mki67, Ccn1, Muc1, Atf3, Ntrk2, Arid5b, Igf1r, Igf2bp2, Cd47, and Cd37 (oncogenic function) and integrin-related genes, Itga7, Itga11, Itgam and Notch1 (cancer stem cell markers)." (PMID 39946195, 2025). "These pathways promote cytoskeletal remodeling, increased motility, and resistance to apoptosis, hallmarks of cancer metastasis (as ITGA7)." (PMID 40076599, 2025). "Based on ITGA7 microarray studies, we found that ITGA7 was significantly low-regulated in many cancers including GC." (PMID 34504842, 2021). "Integrin alpha 7 (ITGA7) was demonstrated to maintain stemness through targeting CSC biomarkers in various cancers." (PMID 33117795, 2020). "At functional level, ITGA7 regulates cancer stem cell properties through FAK-mediated signaling pathways triggered by ligand-integrin interaction." (PMID 28930282, 2017). "Among them, integrin α7 (ITGA7) was chosen for further study because it was only expressed in a small group of cancer cells in both clinical specimens and cell lines." (PMID 27924820, 2016). "Taken together, these results suggested that ITGA7 functionally conferred cancer stemness features in OSCC via activation of the FAK/MAPK/ERK pathway." (PMID 27924820, 2016). "ITGA7 exhibits context-dependent expression patterns across various cancers." (PMID 41235257, 2025). "Due to the complexity of malignant pathological processes, different malignancies may be different in their pathological features and the effect of ITGA7 on cellular function and its potential mechanisms in different cancers may differ." (PMID 36267977, 2022). "Meanwhile, ITGA7 may enhance the stemness of cancer cells, thereby lead to poor differentiation of NSCLC patients, which is validated in our following cellular experiments." (PMID 31418948, 2019). "ITGA7 may activate the mitotic cycle, enhance the adhesion and motility of cancer cells, thereby promotes proliferation in NSCLC cells." (PMID 31418948, 2019). "Western blotting documented a reduced ITGA7 protein level in temsirolimus-resistant cancer cells." (PMID 29721158, 2018). "A recent study showed that integrin α7 (ITGA7) is a functional marker of ESCC cancer stem cells." (PMID 28930282, 2017). "To further investigate if ITGA7 is a functional marker of oesophageal CSCs, we performed similar assays to examine cancer and stemness properties in OSCC cells with ITGA7 stably suppressed." (PMID 27924820, 2016). "Furthermore, we found that some ITGs such as ITGA3, ITGA6 ITGA11, ITGB4, ITGB6, etc. were frequently upregulated in human cancers, whereas ITGs including ITGA1, ITGA7, ITGA8, ITGA9 and ITGB3, etc. were usually downregulated." (PMID 34222028, 2021).
cancer (continued). "We observed that ITGA7 had a direct interaction with ITGBL1 in PPI network, which suggested that they might be coexpressed, and all three genes were upregulated DEGs that regulated cell proliferation, invasion and migration in cancers." (PMID 34409913, 2021). "Importantly, we do not find that low ITGA7 alone is a viable marker of BCSCs, as is evident from the complete absence of expression in any cancer cells in many cancer cases, but that low ITGA7 is associated with some stem-like behaviours such as chemoresistance." (PMID 34253873, 2021). "To further confirm the effect of ITGA7 on cancer stemness is through the FAK-mediated pathway, we studied whether a specific FAK autophosphorylation inhibitor Y15 (1,2,4,5-benzenetetraamine tetrahydrochloride) could abolish ITGA7-induced tumorigenicity and metastasis." (PMID 27924820, 2016).
myopathy (5 papers, 2010 to 2023). A disease of the muscle in which the muscle fibers do not function properly. "Given the association between ITGA7 and myopathy, ITGA7 might be potentially linked with the muscle in PD, considering the motor symptoms." (PMID 35628462, 2022). "In addition, ITGA7 deficiency is common in muscular dystrophy and myopathy." (PMID 34884422, 2021). "Indeed, splicing aberrations in Itga7 which modulate its function are reported to be involved in myopathy." (PMID 35165120, 2022). "The main symptoms of PD are motor function-related symptoms; therefore, we speculated that the motor function-related symptoms of PD may be related to myopathy due to a decrease in ITGA7 expression." (PMID 34884422, 2021).
infection (4 papers, 2018 to 2025). The state of being infected such as from the introduction of a foreign agent such as serum, vaccine, antigenic substance or organism. "The top 5 downregulated genes in the UB of CIE mice at 1 wk post-infection included Igf1, Col6a3, Myrf, Itga7, and Serpinf1." (PMID 36490282, 2022). "A hard-thresholded, mostly relaxed, LASSO-constrained logistic regression model was used to select a parsimonious gene set (ITGB4, ITGA7, IFI27, FAM20A) highly capable of discriminating any bacterial from nonbacterial infection (cross validated AUC = 0.90)." (PMID 40060038, 2025).
bacterial infection (2 papers, 2023 to 2025). "Density plots for the selected genes displayed separate, but overlapping expression patterns with ITGA7, ITGB4 and FAM20A exhibiting higher expression in subjects with bacterial infection and the interferon-related gene IFI27 exhibiting higher expression in subjects lacking a bacterial infection." (PMID 40060038, 2025).
ITGA7 also shares sentences with these, for which no sentence is quoted: prostate carcinoma (5 papers); congenital myasthenic syndrome (2); non-small cell lung carcinoma (2); pulmonary fibrosis (2); Alzheimer disease (1); brain cancer (1); breast invasive carcinoma (1); cervical squamous cell carcinoma (1); COVID-19 (1); developmental delay (1); dilated cardiomyopathy (1); distal myopathy (1); endocervical adenocarcinoma (1); Esotropia (1); Ewing sarcoma (1); gastric cancer (1); heart failure (1); Hernia (1); hypertrophic cardiomyopathy (1); left ventricular non-compact cardiomyopathy (1); leiomyosarcoma (1); lentivirus infection (1); lobular carcinoma (1); lung carcinoma (1); lymph node metastasis (1); malaria (1); malignant pleural mesothelioma (1); mesothelioma (1); movement disorder (1); muscle disorders (1).
A further 8 diseases each share a sentence with ITGA7 in 1 paper.